LUCAT1 (lung cancer associated transcript 1)
Diseases named in the same sentence as LUCAT1 in open-access papers (continued):
Sharing a sentence is not in itself a finding about the gene and the disease.
esophageal squamous cell carcinoma (14 papers, 2019 to 2024). Esophageal squamous cell carcinoma (ESCC) is a type of esophageal carcinoma (EC) that can affect any part of the esophagus, but is usually located in the upper or middle third. "For instance, high expression of lncRNA lung cancer-associated transcript 1 in esophageal squamous cell carcinoma upregulates DNMT protein levels, thereby affecting gene transcription." (PMID 34215719, 2021). "In another example, lncRNA LUCAT1 was found to interact with DNMT1 but now to inhibit the ubiquitination in esophageal squamous cell carcinoma (ESCC)." (PMID 36533073, 2022). "For example, LUCAT1 can promote esophageal squamous cell carcinoma and clear cell renal cell carcinoma tumorigenesis by controlling the ubiquitination and stability of DNMT1 and the AKT/GSK-3β signaling pathway, respectively." (PMID 33097685, 2020). "The cheRNA LUCAT1 promotes the proliferation and metastasis of esophageal squamous cell carcinoma (ESCC) by increasing the stability of DNA methyltransferase 1 (DNMT1) and increases the methylation level of tumor suppressor factors, leading to the proliferation and metastasis of ESCC." (PMID 33937246, 2021). "Additionally, LUCAT1 promotes tumorigenesis by controlling ubiquitination and stability of DNA methyltransferase 1 in esophageal squamous cell carcinoma." (PMID 31399501, 2019). "Yoon et al30 showed that the LUCAT1 expression was overexpressed in oesophageal squamous cell carcinoma (ESCC) tissues and cell lines." (PMID 33787082, 2021). "LncRNA LUCAT1 affects the stability of DNMT1 and decreases the expression of tumor suppressor genes in a way of DNA methylation, thereby inducing tumorigenesis in esophageal squamous cell carcinoma." (PMID 31847842, 2019). "In esophageal squamous cell carcinoma, a distinct model was proposed, in which, the lncRNA LUCAT1 binds DNMT1 to protect it from ubiquitination, while LUCAT1 knock-down promotes ubiquitination of DNMT1 through UHRF1 (Ubiquitin-Like PHD and RING Finger Domain-Containing Protein 1)." (PMID 35292092, 2022). "LUCAT1 dysregulation was observed in various cancers, including non-small-cell lung cancer, glioma, renal cell carcinoma, esophageal squamous cell carcinoma, prostate cancer, cutaneous squamous cell carcinoma, and CRC15–21." (PMID 33097685, 2020).
gastric cancer (14 papers, 2017 to 2025). A primary or metastatic malignant neoplasm involving the stomach. "The expression of lncRNA LUCAT1 is elevated, and its knockdown can effectively reduce the rate at which gastric cancer cells proliferate and metastasize." (PMID 40442738, 2025). "Previous study has proved that LUCAT1 promotes the proliferation and metastasis of gastric cancer by regulating miR-134-5p/YWHAZ axis." (PMID 37550755, 2023). "Linc00511 in non-small cell lung carcinoma, SNHG17 in colorectal, gastric cancer, LUCAT1 (lung cancer associated transcript 1), PVT1, also act through a similar mechanism, involving interaction with PRC2/EED-EZH2 complex." (PMID 35456025, 2022). "For example, lncRNA LUCAT1 fosters cell proliferation and invasion in gastric cancer through targeting miR-134-5p." (PMID 32469064, 2020). "Since LUCAT1 is also highly expressed in gastric cancer, it can be hypothesized that a similar post-translational control also occurs in 23132/87 and MKN45 gastric cancer cells." (PMID 32751694, 2020). "Therefore, the LUCAT1/miR-134-5p complex shows high expression levels in gastric cancer tissues." (PMID 40191723, 2025). "Indeed, highly expressions of both LUCAT1 and MIR210HG were also found in gastric cancer cells." (PMID 37550755, 2023). "TINCR was upregulated in human gastric carcinoma, and TUG1 was upregulated in many cancer tissues and cells; therefore, the increased expression of LUCAT1, TINCR, and TUG1 might not be specific to ACBP and ASLB treatments." (PMID 29156779, 2017).
clear cell renal cell carcinoma (12 papers, 2017 to 2024). "Significant upregulation of LUCAT1 in clear cell renal cell carcinoma (ccRCC) samples has been reported, and in fact, LUCAT1 overexpression induces proliferation, migration and invasion of ccRCC cells by inducing AKT and suppressing GSK3β." (PMID 39594666, 2024). "Previous studies have shown that LUCAT1 promoted proliferation and invasion in clear cell renal cell carcinoma cells through the AKT/GSK-3β signalling pathway." (PMID 32922538, 2020). "In comparison, we also found Lucat1 was ubiquitously expressed at higher levels in a panel of 5 human clear cell renal cell carcinoma lines than immortalized human proximal renal tubule epithelial cell line HK-2." (PMID 29371934, 2017). "Lucat1 acts as an oncogene in clear-cell renal cell carcinoma by binding to polycomb PRC2 complex and suppressing p57." (PMID 29371934, 2017). "LUCAT1 promotes proliferation and invasion of clear cell renal cell carcinoma." (PMID 31399501, 2019).
ovarian carcinoma (12 papers, 2019 to 2025). A malignant neoplasm originating from the surface ovarian epithelium. "For instance, lncRNA LUCAT1 accelerated ovarian cancer progression via the modulation of miRNA-612/HOXA13 pathway." (PMID 35957833, 2022). "It has been verified that LUCAT1 promotes malignant progression of ovarian cancer (OvCa) by regulating the miR-612/HOXA13 pathway." (PMID 35711895, 2022). "Some studies also explore the relationship between LUCAT1 and miRNAs, including miR-514a/b-3b in choroidal melanoma, miR-199a-5p in ovarian cancer, and miR-199b-5p in cervical cancer." (PMID 33097685, 2020). "Two studies about ovarian cancer and overexpression of LUCAT1 have been described and revealed that LUCAT1/miR-612/HOXA13 pathway modulates ovarian cancer progression." (PMID 31591432, 2019). "Interestingly, two reports highlight the role of LUCAT1 in ovarian cancer." (PMID 34204094, 2021).
non-small cell lung carcinoma (11 papers, 2017 to 2025). A group of at least three distinct histological types of lung cancer, including non-small cell squamous cell carcinoma, adenocarcinoma, and large cell carcinoma. "A hyperlink directs users to the detailed result page for the CE lncRNA LUCAT1 in non-small cell lung cancer (NSCLC), derived from GSE117570." (PMID 40833782, 2025). "For example, the expression of LUCAT1 is aberrant in the tissues of patients with non-small-cell lung cancer or hepatocellular carcinoma." (PMID 34414854, 2021). "Other identified lncRNAs included LUCAT1, which is important in non-small cell lung cancer, NEAT1, and HELLPAR." (PMID 28957348, 2017).
osteosarcoma (11 papers, 2018 to 2025). A usually aggressive malignant bone-forming mesenchymal neoplasm, predominantly affecting adolescents and young adults. "For instance, the lncRNA lung cancer associated transcript 1 (LUCAT1) sensitizes osteosarcoma cells to methotrexate by sponging miR-200c, a Pgp inducer." (PMID 32599901, 2020). "Since cell proliferation is closely associated with drug resistance, lncRNA LUCAT1 promotes methotrexate resistance in osteosarcoma by regulating the miR-200c/ABCB1 axis." (PMID 31777598, 2019). "The lncRNA Lung cancer associated transcript 1 (LUCAT1) is specifically overexpressed in osteosarcoma cell-lines resistant to methotrexate (MTX), one of the most effective drugs used in treatment of patients with osteosarcoma." (PMID 29657304, 2018). "Cell lines from osteosarcomas that display resistance to methotrexate, an extremely potent chemotherapeutic agent used in this type of neoplasia, have been demonstrated to contain amplified lung cancer-associated transcript 1 (LUCAT1) expression." (PMID 39015175, 2024). "In addition, LUCAT1 enhances the expression of the genes associated with drug resistance and promotes the proliferation and invasion of osteosarcoma cells." (PMID 31777598, 2019). "The lncRNA LUCAT1 is highly expressed in several cancers, including lung, gastric, ovarian, and osteosarcoma tissues." (PMID 40713875, 2025). "Accordingly, if elevated levels of LUCAT1 were detected in human osteosarcomas, it can be used as a predictive biomarker in individuals with osteosarcomas." (PMID 39015175, 2024). "Recently, a novel lncRNA LUCAT1 was reported to be up‐regulated in several tumours such as lung tumour, glioma, osteosarcoma, renal carcinoma and oesophageal squamous cell carcinoma." (PMID 33787082, 2021). "Consequently, high LUCAT1-levels could serve as predictive biomarkers in patients with osteosarcoma regarding MTX-sensitivity, provided that further experiments show that LUCAT1 is also overexpressed in human osteosarcoma tissue samples." (PMID 29657304, 2018). "In fact, LUCAT1 has been found to be upregulated in multiple cancers, including non-small-cell lung carcinoma (NSCLC), esophageal cancer, renal cell carcinoma, and osteosarcoma." (PMID 39594666, 2024).
hepatocellular carcinoma (10 papers, 2019 to 2025). A malignant tumor that arises from hepatocytes. "A long non-coding RNA, named lung cancer-associated transcript 1 (LUCAT1), induced cell growth and metastasis of hepatoma cell lines in vitro and in vivo." (PMID 34575275, 2021). "Accordingly, LUCAT1 regulates the proliferation, migration, and invasion of hepatocellular carcinoma cells and esophageal cancer." (PMID 40191723, 2025). "LUCAT1 functions as a ceRNA in hepatocellular carcinoma tissues, binding to and downregulating miR-181d-5p, thereby enhancing cellular proliferation, migration, and invasion." (PMID 40191723, 2025). "Lung cancer‐associated transcript 1 (LUCAT1) has been reported in a variety of human cancers, while its role in hepatocellular carcinoma (HCC) remains unclear." (PMID 30588744, 2019). "LUCAT1 is also found in blood serum exosomes of hepatocellular carcinoma patients." (PMID 32655720, 2020). "LUCAT1 can activate the metalloproteinase protein, regulating the expression of DLC1, and enhance the malignant phenotype of hepatoma cells." (PMID 34901153, 2021).
glioma (9 papers, 2019 to 2024). A benign or malignant brain and spinal cord tumor that arises from glial cells (astrocytes, oligodendrocytes, ependymal cells). "Abnormal expression of lung cancer associated transcript 1 (lncRNA LUCAT1) can affect glioma cell proliferation by regulating ABCB1 and promoting the activation of the RAS signaling pathway." (PMID 38967893, 2024). "Abnormal expression of LUCAT1 affects glioma cell biology by regulating ABCB1 and promoting the activation of the RAS pathway." (PMID 39896807, 2024). "Gao et al32 found that the expression of LUCAT1 was up‐regulated in glioma cell lines and specimens." (PMID 33787082, 2021). "LUCAT1 knockdown decreased the glioma cell invasion and proliferation partly through regulating the miR‐375 expression." (PMID 33787082, 2021). "Knockdown expression of LUCAT1 decreased the glioma cell invasion and proliferation partly through regulating the miR‐375 expression." (PMID 33787082, 2021). "LUCAT1 is an oncogenic molecule in glioma, and its knockdown induced inhibition of cell viability and invasion by regulating miR-375 in glioma." (PMID 34950662, 2021). "Gao et al32 found that the expression of LUCAT1 was up‐regulated in the glioma cells and samples." (PMID 33787082, 2021). "In addition, it has been shown that LUCAT1 increased the glioma cell invasion and proliferation through regulating miR‐375 expression." (PMID 33787082, 2021).
cervical cancer (6 papers, 2020 to 2021). A primary or metastatic malignant neoplasm involving the cervix. "To date, several studies have verified LUCAT1/miR-181a axis, miR-181a-5p/TGFβI axis and miR-181a-5p/MMP14 axis in cervical cancer." (PMID 32849815, 2020).
liver cancer (6 papers, 2019 to 2023). An epithelial or non-epithelial malignant neoplasm that arises from the liver. "High LUCAT1 expression was an independent prognostic factor for liver cancer." (PMID 32922538, 2020). "To confirm the elevated expression of LUCAT1 in HCC tissues, we first examined its expression levels in 90 pairs of liver cancer and adjacent non‐cancerous tissues by qRT‐PCR." (PMID 30588744, 2019).
lung adenocarcinoma (6 papers, 2017 to 2025). A carcinoma that arises from the lung and is characterized by the presence of malignant glandular epithelial cells. "For instance, LUCAT1 facilitates glycolysis and metastasis of lung adenocarcinoma cells by functioning as a competing endogenous RNA that regulates the miR-4316/VEGFA axis." (PMID 39167430, 2024). "Studies have found that LUCAT1 can promote the metastasis of lung adenocarcinoma cells and glycolysis by regulating the miR-4316/VEGFA axis." (PMID 36401283, 2022).
bladder cancer (5 papers, 2020 to 2025). "Collectively, our study highlights the clinical relevance of LUCAT1 as a potential tumor biomarker and underscores its promise as both a diagnostic and therapeutic target for bladder cancer." (PMID 40025525, 2025). "Taken together, these findings indicate that LUCAT1 promotes chemoresistance in bladder cancer cells by enhancing their stemness." (PMID 40025525, 2025). "Further experimental results demonstrated that LUCAT1 promotes chemoresistance in bladder cancer by enhancing the stemness phenotype of BC cells in vivo and in vitro." (PMID 40025525, 2025). "Our analysis revealed a marked upregulation of multiple tumor-associated lncRNAs, including LUCAT1, in GEM-resistant bladder cancer organoids, highlighting their potential role in chemoresistance mechanisms." (PMID 40025525, 2025). "Additionally, developing safe and effective interventions targeting the LUCAT1/IGF2BP2/HMGA1 signaling axis to effectively inhibit the stemness transformation of bladder cancer cells and suppress chemotherapy resistance warrants further investigation." (PMID 40025525, 2025). "We conducted comprehensive lncRNAs expression profile analyses to identify lncRNAs involved in chemoresistance of bladder cancer and found LUCAT1 expression is significantly up-regulated in chemotherapy-resistant BC (BC-CR) cells compared to chemotherapy-sensitive BC (BC-CS) cells." (PMID 40025525, 2025). "Moreover, exosomes derived from bladder cancer stem cells can enhance the stemness phenotype and chemoresistance of BC cells by delivering LUCAT1." (PMID 40025525, 2025). "Moreover, the suppression of the malignant phenotype in bladder cancer (BC) cells induced by LUCAT1 silencing was reversed upon HMGA1 overexpression, highlighting its functional relevance." (PMID 40025525, 2025). "Further investigation into LUCAT1-mediated regulatory networks could pave the way for novel therapeutic strategies aimed at targeting resistant tumor cell populations and improving treatment efficacy in bladder cancer." (PMID 40025525, 2025). "Consistently, our findings demonstrated that LUCAT1 expression was significantly elevated in GEM-resistant BC cells, and LUCAT1 promotes chemoresistance in bladder cancer cells by enhancing their stemness." (PMID 40025525, 2025). "Several lncRNAs, including LINC00839, lncRNA PVT1, LUCAT1, LINC00958, and BCYRN1, exert a positive influence on both the proliferative viability and invasive capabilities of bladder cancer cells." (PMID 39628486, 2024). "Exosome-transmitted LUCAT1 promotes the stemness phenotype and chemoresistance of BC cells via upregulating HMGA1 expression via binding to IGF2BP2, thus contributing to its oncogenic activity in bladder cancer pathogenesis." (PMID 40025525, 2025). "Remarkably, LUCAT1 was significantly up-regulated in bladder cancer tissues comparing to paired nonneoplastic tissues, and a positive correlation was observed between higher LUCAT1 expression and advanced T stage as well as higher histological grade and poor prognosis." (PMID 40025525, 2025). "Our investigation has revealed that cancer stem cell-derived exosomal LUCAT1 enhances the stemness phenotype and chemoresistance of bladder cancer cells by upregulating HMGA1 expression through its interaction with IGF2BP2, thereby contributing to the oncogenicity of bladder cancer." (PMID 40025525, 2025).
renal carcinoma (5 papers, 2017 to 2022). A carcinoma arising from the epithelium of the renal parenchyma or the renal pelvis. "In the present study, we found that the expressions of SNHG17, RUSC1-AS1, LINC02609, and LUCAT1 were significantly increased while the expression of DOCK8-AS1 was significantly decreased in the patients with renal cancer and in renal cancer patients with high-risk values." (PMID 35118117, 2021). "LUCAT1 promotes proliferation and invasion of renal cancer through the AKT/GSK-3β signalling pathway." (PMID 34736453, 2021). "The expression of DOCK8-AS1 was significantly decreased, while the expressions of those 4 signatures (SNHG17, RUSC1-AS1, LINC02609, and LUCAT1) were significantly increased in the patients with renal cancer." (PMID 35118117, 2021). "Xiao et al29 indicated that LUCAT1 expression was up‐regulated in the renal carcinoma specimens and overexpression of LUCAT1 increased cell proliferation." (PMID 33787082, 2021). "A diagnostic model integrating those 5 FR-DELs (DOCK8-AS1, SNHG17, RUSC1-AS1, LINC02609, and LUCAT1) was established to separate patients with renal cancer from the normal group by using a stepwise logistic regression method." (PMID 35118117, 2021). "The expression of DOCK8-AS1 was significantly decreased, while the expressions of SNHG17, RUSC1-AS1, LINC02609, and LUCAT1 were increased significantly in patients with renal cancer." (PMID 35118117, 2021). "It showed that sh-Lucat1 can promote the expression of p57, whereas sh-p57 can relieve the promotion of p57 by Lucat1 in renal cancer cell lines ACHN and 768-O." (PMID 29371934, 2017). "Further assay of transwell showed that knockdown Lucat1 suppressed renal cancer cell migration and invasion." (PMID 29371934, 2017). "To explore the role of Lucat1 in renal cancer cells, we stably inhibited Lucat1 in two ccRCC cell lines ACHN and 786-O with lenti-viruses carrying shRNA for Lucat1 and a control nonspecific shRNA (LacZ)." (PMID 29371934, 2017). "Functional assays showed that Lucat1 can promote renal cancer cell proliferation in vitro and in vivo." (PMID 29371934, 2017). "We also found that Lucat1 is capable of facilitating cell growth, migration and invasion through epigenetically suppressing p57 in renal cancer cell lines." (PMID 29371934, 2017). "Our data indicated that Lucat1 has higher expression in renal cancer cell lines and renal cancer tissues." (PMID 29371934, 2017). "Finally, we identified 5 FR-DELs (DOCK8-AS1, SNHG17, RUSC1-AS1, LINC02609, and LUCAT1) correlated with the OS of renal cancer patients independently through a series of bioinformatics analyses." (PMID 35118117, 2021). "To determine whether those 5 FR-DELs (DOCK8-AS1, SNHG17, RUSC1-AS1, LINC02609, and LUCAT1) could be prognosis signatures for renal cancer, we used the validation group data and entire group data for verification." (PMID 35118117, 2021). "In the present study, we identified 5 FR-DELs (DOCK8-AS1, SNHG17, RUSC1-AS1, LINC02609, and LUCAT1) that could be used as biomarkers to predict the outcome of renal cancer." (PMID 35118117, 2021). "Previous studies also demonstrated that LUCAT1 is correlated with OS and could be used as a prognostic signature for several cancers, such as papillary thyroid cancer, non-small lung cancer, and renal cancer." (PMID 34736453, 2021). "In the present study, we also found that LUCAT1 could use as a prognostic biomarker for renal cancer." (PMID 35118117, 2021). "The ROC curve suggested that the risk assessment model constructed by those 5 FR-DELs (DOCK8-AS1, SNHG17, RUSC1-AS1, LINC02609, and LUCAT1) could be used for prognosis signatures for renal cancer patients." (PMID 35118117, 2021). "Particularly, we found that the distribution of renal cancer patients with low-risk values was relatively concentrated, which could be well distinguished from renal cancer patients with high-risk values by using those 5 FR-DELs (DOCK8-AS1, SNHG17, RUSC1-AS1, LINC02609, and LUCAT1)." (PMID 35118117, 2021).